TPD52 (tumor protein D52)
Diseases named in the same sentence as TPD52 in open-access papers (continued):
Sharing a sentence is not in itself a finding about the gene and the disease.
prostate carcinoma (39 papers, 2010 to 2025). A carcinoma that arises from epithelial cells of the prostate gland. "Dysregulation of TPD52, resulting from chromosomal amplification and androgen induction, has been implicated in prostate cancer development." (PMID 40341647, 2025). "Another DTU gene, TPD52, which has a short isoform encoding PrLZ, is a biomarker of prostate cancer and has an anti-apoptotic function." (PMID 34811492, 2021). "Previously, elevated TPD52 expression in prostate cancer was reported to have association with tumor progression and metastasis." (PMID 33490232, 2020). "In addition, the results of multivariate Cox regression showed that only LINC01122, TPD52, and T stage were independent risk factors for the prognosis of prostate cancer patients." (PMID 40341647, 2025). "For TPD52, its overexpression has been described from a multitude of cancer types, including breast, prostate, ovarian, and has been linked to poor prognosis in breast and prostate cancer patients." (PMID 26883192, 2016). "miR-218, miR-224, and miR-103a-3p inhibited the growth, invasion, and metastasis of prostate cancer cells and promoted apoptosis via the downregulation of TPD52 expression." (PMID 40973691, 2025). "In prostate cancer, chaperone‐mediated autophagy is modulated by acetylation‐dependent regulation of TPD52." (PMID 39757112, 2025). "The mechanism is that circ‐XIAP can directly target miR‐1182 and subsequently promote multidrug resistance in prostate cancer by regulating the miR‐1182/TPD52 axis, which is a promising therapeutic target for prostate cancer chemotherapy." (PMID 39239069, 2024). "The exogenous overexpression of PrLZ, a splice variant of TPD52, in prostate cancer cells leads to accelerated growth in vitro and tumor formation in vivo." (PMID 39767632, 2024). "In prostate cancer, the protein TPD52 has been observed to activate CMA through its interaction with HSPA8/HSC70, leading to enhanced substrate degradation." (PMID 39403142, 2024). "The upregulation of TPD52 is crucial for promoting growth and stress resistance in prostate cancer cells." (PMID 39403142, 2024). "A recent experiment has shown involvement of TPD52 in docetaxel resistance of prostate cancer cells via inhibiting autophagy and subsequent docetaxel-mediated apoptosis." (PMID 35317831, 2022). "The tumor protein D52 (TPD52) is amplified from the human chromosome 8q21 amplification region to an oncogene and is highly expressed in many cancers, such as ovarian cancer and prostate cancer." (PMID 35433464, 2022). "In respect to the tumor-promoting role of TPD52, its activation remarkably promotes progression of prostate cancer cells." (PMID 35317831, 2022). "Exposing prostate cancer cells to docetaxel inhibits TPD52 and STK11/LKB1 (serine/threonine kinase 11) interaction to promote STK11 expression." (PMID 35317831, 2022). "TPD52/PrLZ/prostate leucine zipper (tumor protein D52) localized on chromosome 8q21.1 has specific expression in prostate tissues and it demonstrates upregulation in advanced prostate cancer." (PMID 35317831, 2022). "The PrLZ form of Tumour Protein D52 (TPD52) has a well-characterized role in prostate cancer progression." (PMID 33446905, 2021). "Research shows that both estradiol and androgen affect the tumor protein D52 expression which is considered as vital signaling molecules in breast and prostate cancer respectively." (PMID 34099820, 2021). "The same results were observed when we determined the consequence of downregulation of TPD52 on the invasiveness of prostate cancer cells, (standard in vitro chamber assays with a matrigel model were performed)." (PMID 34099820, 2021). "TPD52, protein has a high level of expression in prostate cancer and the expression decreased significantly after treatment with MEM in xenograft tumors of athymic nude mice as demonstrated by western blot analysis." (PMID 34099820, 2021).
prostate carcinoma (continued). "Downregulation of TPD52 inhibited the migration and invasive behavior of prostate cancer cells as observed." (PMID 34099820, 2021). "Prostate cancer death occurs in men with high-grade late-stage cancer; we tried to observe the oncogenic expression of TPD52 in the TRAMP model." (PMID 34099820, 2021). "Immunohistochemical analysis of a large group of prostate cancers showed that marked TPD52 overexpression occurred in virtually all grades from early-stage prostate cancer to high-grade prostate cancer." (PMID 34099820, 2021). "Our results were consistent with previous studies in which TPD52 expression was found to be significantly increased in ovarian and prostate cancer." (PMID 33490232, 2020). "Tumor protein D52 (TPD52) is amplified and overexpressed in breast and prostate cancers which are frequently characterised by dysregulated lipid storage and metabolism." (PMID 31278300, 2019). "The tumor protein D52 (TPD52) is frequently and strongly upregulated in many human cancer types and this trend is observed in various urogenital cancers among which is prostate cancer as well." (PMID 25215235, 2014). "Moreover, overexpression of TPD52 leads to an increase in cell proliferation and phosphorylation of protein kinase B (Akt) in prostate cancer and protects these cells from apoptosis induced by androgen deprivation." (PMID 39767632, 2024). "Acetylation‐dependent regulation of TPD52 modulates CMA oncogenic function in prostate cancer." (PMID 37143582, 2023). "However, TPD52 upregulation in drug resistant-prostate cancer cells leads to STK11 and AMPK downregulation and subsequent inhibition of autophagy." (PMID 35317831, 2022). "In a study investigating the impact of miR-103a-3p on prostate cancer (PCa) cells, enhancement of miR-103a-3p inhibited migration and invasion of PCa cells by regulating the expression of the oncogenic tumor protein D52 (TPD52)." (PMID 35094292, 2022). "Therefore, by using a prostate cancer tissue microarray, we were able to differentiate protein expression of TPD52 in a wide variety of prostate samples." (PMID 34099820, 2021). "Downregulation of TPD52 inhibited the migration of prostate cancer cells." (PMID 34099820, 2021). "Hence, we evaluated the expression of TPD52 in transgenic adenocarcinoma of the mouse prostate (TRAMP) as prostate cancer development and progression have been well characterized in this model." (PMID 34099820, 2021). "Moreover, Expression of TPD52 was observed in all of the tested prostate cancer cell lines (RWPE, C4-2, Du145, CWR22Rν1, PC3, LnCap, and NB26) under regular culture conditions." (PMID 34099820, 2021). "We observed the expression of TPD52 in prostate tissue lysates of TRAMP mice (8, 24, 36 weeks) and the results showed that with the increase of tumor size and growth the expression of TPD52 increased which is again in favor that TPD52 is overexpressed in high stage prostate cancer." (PMID 34099820, 2021). "Moreover, TPD52 was demonstrated to promote tumorigenesis and metastasis of NIH3T3 fibroblasts and TPD52 exogenous overexpression enhanced cellular migration of prostate cancer." (PMID 28562687, 2017). "Besides, TPD52 might up-regulate the PSA an acknowledged downstream target gene of the androgen receptor which showed TPD52 mediated the tumor growth of prostate cancer was related to signals of androgen." (PMID 34099820, 2021). "Moreover, through repressing TPD52 expression, miR-218 could inhibit prostate cancer growth and promote apoptosis." (PMID 28030804, 2017). "Tumor protein D52 (TPD52) mediated the activation of CMA and promoted the proliferation and metastasis of prostatic cancer (PCa)." (PMID 40083922, 2025). "The present research demonstrated the expression of TPD52 in tumor cell lines in order of increasing malignancy and invasiveness which is RWPE < NA22 < NB14 < NB11 < NB26 (progression model of prostate cancer) described by the laboratory of Webber (2001)." (PMID 34099820, 2021).
prostate carcinoma (continued). "TPD52 was in general low in normal secretory epithelia and benign prostatic hyperplasia (BPH) however overexpressed in intraepithelial neoplasia high-grade prostate tissue and prostate cancer." (PMID 34099820, 2021). "Hence, the effects of the downregulation of TPD52 on the PSA level of cells correlate with inhibition of growth and proliferation of prostate cancer cells." (PMID 34099820, 2021). "We confirm alterations in six genes previously associated with prostate cancer (MAP3K7, MELK, RCBTB2, ELAC2, TPD52, ZBTB4), and also identify 94 genes not previously linked to prostate cancer progression that would not have been detected using either transcript or copy number data alone." (PMID 26501111, 2015).
ovarian carcinoma (15 papers, 2007 to 2024). A malignant neoplasm originating from the surface ovarian epithelium. "High TPD52 staining was associated with significantly improved overall patient survival in ovarian carcinoma." (PMID 20846453, 2010). "Tumour protein D52 isoform 2 (TPD52) encoded by a gene at 8q21.1 is described as the target for amplification of this region in breast and ovarian cancers." (PMID 18059402, 2007). "The differential association of high TPD52 staining and overall patient survival in breast versus ovarian carcinoma may indicate different roles for TPD52 overexpression in ovarian versus breast tumour progression." (PMID 20846453, 2010). "Our pathway analysis reveals that TPD52 influences the activation of many signaling proteins, hence increasing ovarian cancer." (PMID 37833790, 2023). "TPD52 expression was greater advanced-stage ovarian cancer and those with distant metastases compared to healthy controls." (PMID 37833790, 2023). "Compared to healthy controls, the expression of TPD52 (19.79 ± 0.42) was higher in ovarian cancer patients." (PMID 37833790, 2023). "This led us to conclude that TPD52 and miR-223 are likely involved in the development of ovarian cancer." (PMID 37833790, 2023). "Increased TPD52 expression and gene copy number have been reported in breast, prostate and ovarian cancer increasing cell proliferation in vitro and tumorigenicity in mice." (PMID 22589739, 2012). "This agrees with our previous finding that TPD52 was broadly overexpressed in an independent ovarian carcinoma cohort." (PMID 20846453, 2010). "Other studies have similarly reported increased TPD52 expression in ovarian cancer using expression microarray and proteomic approaches." (PMID 20846453, 2010). "The aim of the present study was therefore to define MAL2 and TPD52 expression in a large cohort of ovarian carcinomas, relative to other clinical parameters." (PMID 20846453, 2010). "In contrast, increased TPD52 staining was noted to be a favourable prognostic marker in ovarian carcinoma." (PMID 20846453, 2010). "MAL2 is frequently overexpressed in ovarian carcinoma, and TPD52 overexpression is a favourable independent prognostic marker of potential value in the management of ovarian carcinoma patients." (PMID 20846453, 2010). "Given that TPD52 expression is elevated in every occurrence of ovarian cancer, it may be a valuable biomarker for early disease detection." (PMID 37833790, 2023). "TPD52 mRNA levels were observed to be upregulated in ovarian cancer patients relative to control." (PMID 37833790, 2023). "Consistently, the poor prognosis was also observed in TPD52-high NSCLC or ovarian cancer patients." (PMID 31649118, 2019). "Another research also found that increased TPD52 expression might be a favorable prognostic marker in ovarian carcinoma." (PMID 26575170, 2016). "In ovarian cancer, TPD52 overexpression has been identified in all histological subtypes of ovarian carcinoma relative to normal ovarian epithelium, with a significant positive correlation between TPD52 expression and gene copy number being found in an independent serous carcinoma cohort." (PMID 20846453, 2010). "Thus, whereas increased TPD52 expression appears to be a common event in both breast and ovarian carcinoma, the contrasting clinical significance of both TPD52 overexpression and chromosome 8q21 gain suggests different roles for TPD52 in these cancer types." (PMID 20846453, 2010). "MAL2 binds tumor protein D52 (TPD52), which is frequently overexpressed in ovarian carcinoma, but the clinical significance of MAL2 and TPD52 overexpression was unknown." (PMID 20846453, 2010). "Alternatively, a comparative lack of TPD52 expression could segregate with adverse prognostic markers in ovarian carcinoma, and thus the association between increased TPD52 expression and improved overall survival may be indirect." (PMID 20846453, 2010).
ovarian carcinoma (continued). "Further study revealed that TPD52 mRNA and miRNA-223 expression was elevated, while the expression of KLF 9 and PKCε was reduced in the blood of ovarian cancer patients." (PMID 37833790, 2023). "TPD52, KLF9, PKCε, and miR-223 expression levels were compared between ovarian cancer patients and healthy controls." (PMID 37833790, 2023). "To address this, we compared the expression of TPD52 to KLF 9, PKCε, and miR-223 in ovarian cancer patients and healthy persons." (PMID 37833790, 2023). "The expression of genes TPD52, PKCε, KLF9, and miR-223 in the peripheral blood of ovarian cancer patients was studied in the present investigation, that indicated the expression of TPD52 as well as miR-223 were elevated." (PMID 37833790, 2023). "In ovarian cancer, LINC01133 upregulates tumor protein D52 (TPD52) levels through sharing the same binding sites with miR-495-3p, acting as a pro-metastatic factor." (PMID 35055115, 2022). "MAL2 binds tumor protein D52 (TPD52),which is over-expressed in ovarian carcinoma, and we have shown that MAL2 isfrequently over-expressed in all histological subtypes of ovarian cancer." (PMID 21423607, 2011). "Therefore, in present investigation, we determined the co-expression of TPD52, PKCε, KLF9, and miR-223 in ovarian cancer." (PMID 37833790, 2023). "Additional studies on the roles, pathways, and interactions of TPD52, KLF9, miR-223, and PKC may give valuable insights into the progression of ovarian cancer and assist in identifying novel therapeutic targets." (PMID 37833790, 2023). "This shows that TPD52 expression is more significant in early-stage and non-metastatic ovarian cancer than in later-stage cancer and distant metastases." (PMID 37833790, 2023). "At present, some literatures have reported that TPD52 is highly expressed in ovarian cancer tissues and acts as a downstream signal molecule in some processes, indicating that TPD52 also plays an important role in the occurrence and development of ovarian cancer, and MAL2 and TPD52 are chaperones." (PMID 35111745, 2021). "We also found that TPD52 expression was significantly higher both in NSCLC and ovarian cancer." (PMID 31649118, 2019).
osteosarcoma (9 papers, 2019 to 2025). A usually aggressive malignant bone-forming mesenchymal neoplasm, predominantly affecting adolescents and young adults. "The study revealed that TPD52 antiserum exhibits strong anti-osteosarcoma effects, primarily by inducing apoptosis and activating the immune response." (PMID 40988998, 2025). "In vitro, TPD52 antiserum inhibited osteosarcoma cell proliferation, while in vivo it significantly reduced osteosarcoma tumor growth in mice." (PMID 40988998, 2025). "MG-63 osteosarcoma cells and osteosarcoma-induced mice were treated with TPD52 antiserum, obtained by immunization of mice with recombinant TPD52." (PMID 40988998, 2025). "Anti-TPD52 demonstrated significant anti-cancer activity against osteosarcoma in both in vitro and in vivo experiments, outperforming anti-T." (PMID 40402283, 2025). "spiralis antiserum and antiserum prepared against TPD52, a shared antigen between T. spiralis and osteosarcoma, on osteosarcoma cells." (PMID 41387891, 2025). "In another study, anti-TPD52 antiserum was developed against the cross-antigen gene tumor protein D52 (TPD52) found in human osteosarcoma and T. spiralis." (PMID 39367471, 2024). "Antiserum against the cross antigen TPD52 between osteosarcoma and T. spiralis can inhibit osteosarcoma by inducing apoptosis, without causing distinct pathological damage." (PMID 34565443, 2021). "TPD52 antigen was selected, its antiserum was prepared, and its anti-osteosarcoma effect was examined." (PMID 34565443, 2021). "Our preliminary studies have shown that anti-TPD52 antiserum can exert anti-osteosarcoma effects by promoting the secretion of antitumour cytokines." (PMID 34565443, 2021). "Anti-TPD52 antiserum inhibited the proliferation of MG-63 cells and the growth of osteosarcoma in a dose-dependent manner." (PMID 34565443, 2021). "The effects of anti-TPD52 antiserum on osteosarcoma were assessed by determining the size and weight of tumours." (PMID 34565443, 2021). "We also found that anti-TPD52 antiserum can exert an anti-osteosarcoma effect by inducing apoptosis." (PMID 34565443, 2021). "The anti-osteosarcoma effect of the anti-TPD52 antiserum was studied using cell proliferation and cytotoxicity assays as well as in vivo animal models; preliminary data on the mechanism were obtained using western blot and immunohistochemistry analyses." (PMID 34565443, 2021). "This study initially found that anti-TPD52 antiserum inhibited the growth of osteosarcoma by inducing apoptosis and enhancing immunity." (PMID 34565443, 2021). "Laser confocal microscopy results revealed that green fluorescence existed mainly in the cytoplasm, providing evidence that cross antigen TPD52 between osteosarcoma and T. spiralis was localized in the cytoplasm of MG-63 cells." (PMID 34565443, 2021). "The last, unique study investigated whether antibodies against TPD52 Trichinella protein, can inhibit osteosarcoma cell proliferation and tumor growth, as Trichinella has reported anti-tumor properties." (PMID 40988998, 2025). "TPD52 is a cross antigen between T. spiralis and osteosarcoma." (PMID 40988998, 2025). "In a mouse model of osteosarcoma, the anti-TPD52 antiserum was more effective than the anti-T." (PMID 39367471, 2024). "Thus, the anti-TPD52 antiserum significantly inhibited osteosarcoma growth by inducing apoptosis and enhancing immunity." (PMID 39367471, 2024). "Several studies identified overexpression of the TPD52 gene in osteosarcoma cell lines." (PMID 39411371, 2024). "In this study, cross antigen TPD52 between human osteosarcoma and T. spiralis was identified." (PMID 34565443, 2021). "This study found that anti-TPD52 antiserum has a curative effect on osteosarcoma in vivo." (PMID 34565443, 2021). "Apoptosis of osteosarcoma cells was induced by anti-TPD52 antiserum in vivo and in vitro." (PMID 34565443, 2021). "Anti-TPD52 antiserum exerts an anti-osteosarcoma effect by inducing apoptosis without causing histopathological damage." (PMID 34565443, 2021).
osteosarcoma (continued). "To study the role of cross antigens between osteosarcoma and T. spiralis, we first screened the cDNA expression library of T. spiralis muscle larvae to obtain the cross antigen gene tumour protein D52 (TPD52), and prepared fusion protein TPD52 and its antiserum." (PMID 34565443, 2021). "Osteosarcoma-bearing nude mice were used to test the effect of anti-TPD52 antiserum in vivo." (PMID 34565443, 2021).